INS (insulin)
Diseases named in the same sentence as INS in open-access papers (continued):
Sharing a sentence is not in itself a finding about the gene and the disease.
polycystic ovary syndrome (continued). "Overall, a combination of overfeeding and hyperandrogenemia resulted in a prooxidative and insulin-resistant state in skeletal muscle." (PMID 37371678, 2023). "Polycystic ovary syndrome is more prevalent in SA women and is related to higher insulin concentrations." (PMID 36729923, 2023). "Insulin‐sensitising drugs (metformin, rosiglitazone, pioglitazone, D‐chiro‐inositol) for women with polycystic ovary syndrome, oligo amenorrhoea and subfertility." (PMID 36578840, 2022). "The key pathogenetic factors include hyperandrogenemia, subclinical inflammation, and defective insulin signaling." (PMID 35206286, 2022). "SLC6A4 5HTTLPR polymorphism was revealed to be related to insulin blood levels and insulin secretion during OGTT in patients with polycystic ovary syndrome (PCOS)." (PMID 35837294, 2022). "PCOS is typically characterized by chronic anovulation, elevated androgen levels, a distorted luteinizing hormone/follicle-stimulating hormone (LH/FSH) ratio, irregular menstrual cycle, appearance of polycystic ovaries, and insulin resistance." (PMID 35615684, 2022). "This compound is widely prescribed for the treatment of insulin resistant states, such as polycystic ovary syndrome and for diabetic neuropathy, due to the amount of supporting evidence." (PMID 36615676, 2022). "The included articles dealt with “HS manifestation and exacerbation” (7%), “sexual hormones” (14%), “anti-androgen therapy” (29%), “thyroid function” (21%), “polycystic ovary syndrome” (5%), and “insulin resistance and adipokines” (24%)." (PMID 36499573, 2022). "Both visceral adiposity and hyperandrogenemia are well-documented insulin signaling impairment factors." (PMID 36012206, 2022). "In clinically suspected patients with polycystic ovary syndrome, if there are extremely high blood levels of insulin in the blood, genetic testing should be performed to detect insulin receptor gene mutation of type A insulin resistance syndrome." (PMID 33728347, 2021). "At present, the clinical treatment PCOS ovulation dysfunction infertility patients are mainly treated with ovulation promotion drugs, insulin sensitizer, hyperandrogenemia drugs and other drugs." (PMID 33725936, 2021). "Polycystic ovary syndrome is a disease with an endocrine disorder and the development of PCOS may be caused due to the imbalance in the levels of sex hormones, inflammatory factors, and insulin." (PMID 33746783, 2021). "This does not exclude a bidirectional relationship between hyperandrogenemia and IR, although we suggest that the effect of IR on androgen secretion is likely far greater than the effect of hyperandrogenemia on insulin sensitivity, based on our findings." (PMID 33901270, 2021). "For example, research shows the efficacy of myo-inositol (MI) and D-chiro-inositol (DCI) (insulin-sensitizing agents) in polycystic ovary syndrome." (PMID 34362406, 2021). "This study aimed to compare the effects of oral insulin sensitizers on endocrine and metabolic profiles in women with polycystic ovary syndrome (PCOS)." (PMID 34407851, 2021). "In many cases, weight loss serves as a first promising and meaningful measure, as it improves insulin sensitivity, hyperandrogenemia and irregular menstrual cycles." (PMID 33798258, 2021). "Insulin is also the primary regulator of the production of sex hormone–binding globulin (SHGB) among women with polycystic ovary syndrome (PCOS)." (PMID 34139003, 2021). "Insulin plays a central role in polycystic ovary syndrome, and it engages with the insulin-like growth factor 1 receptor to enhance steroid production in ovaries and adrenal glands." (PMID 34088325, 2021). "Based on modern medical researches, Guizhi Fuling Wan has an excellent anti-inflammatory effect and the ability to improve insulin resistance, usually used to treat chronic pelvic inflammatory disease and polycystic ovary syndrome." (PMID 32973686, 2020).
polycystic ovary syndrome (continued). "Since 1994, metformin has been used as an insulin sensitizer for the treatment of polycystic ovary syndrome." (PMID 33014044, 2020). "The prescription of metformin, an insulin sensitizer, in polycystic ovarian disease slightly improves ovulation, although the conception rate remains disappointing." (PMID 32917200, 2020). "The use of inositol is widespread in endocrinologic clinical practice, especially for its insulin-sensitizing activity, largely exploited for the treatment of polycystic ovary syndrome (PCOS)." (PMID 32392776, 2020). "Its diet supplementation was found to increase the effect of insulin in patients with the polycystic ovary syndrome, improving ovulatory function and decreasing serum androgen concentrations, blood pressure, and plasma triglyceride concentrations." (PMID 33255896, 2020). "Insulin and its receptor (INSR) have been implicated in the etiology of the polycystic ovarian syndrome (PCOS)." (PMID 33033446, 2020). "This study aims to investigate the effects of oolong tea catechins on the uterus of polycystic ovary syndrome (PCOS) mice induced by insulin combined with human chorionic gonadotropin (hCG)." (PMID 33292347, 2020). "Although its pathogenesis is poorly understood, the role of insulin in the pathogenesis of hyperandrogenemia in PCOS is central." (PMID 32542134, 2020). "Decreased phosphorylation of CAV1 at residue Y14 was related to the insulin-resistant state in endometrial tissue of polycystic ovary syndrome patients." (PMID 31442208, 2019). "Mechanistically, hyperandrogenemia in the presence of WSD increases insulin-stimulated FFA uptake and inhibits lipolysis in omental WAT, favoring the development of intra-abdominal obesity in NHPs36,59,61, while the mechanism remains poorly understood." (PMID 31848372, 2019). "A smart in vitro study in granulosa cells from an ovum from a polycystic ovary highlighted that insulin encourages formation of estradiol in cultured human granulosa cells." (PMID 32082253, 2019). "Obese women suffer from insulin and leptin resistance, inducing hyperandrogenemia, modulation of steroidogenesis and polycystic ovaries syndrome (PCOS)." (PMID 32082253, 2019). "Androgen-induced rodent PCOS models, based on DHEA, DHT or testosterone- present hyperandrogenemia, anovulation, cystic ovaries and development of impaired insulin/glucose metabolism." (PMID 29793502, 2018). "Meanwhile, hyperandrogenemia would also impair insulin secretion through disruption of β-cell mitochondrial function, finally resulting in higher blood glucose levels." (PMID 29707577, 2018). "It is thought that the peripheral effects of insulin signaling and the body’s resistance to it account for the differential expression of MetSyn observed across individuals and its associated conditions such as polycystic ovary syndrome (PCOS)." (PMID 29462993, 2018). "Insulin also contributes to hyperandrogenemia in PCOS women by lowering the liver production of sex hormone-binding globulin (SHBG), which acts as a testosterone carrier in plasma and thus lowers free testosterone levels." (PMID 29971102, 2018). "Insulin indirectly exacerbates hyperandrogenemia by reducing hepatic biosynthesis of sex hormone binding globulin and increasing the free and bioavailable testosterone levels." (PMID 29670770, 2018). "Management approaches for metabolic disorders include treatment with metformin and thiazolidinediones, which appear to decrease insulin levels and hyperandrogenemia in women with PCOS." (PMID 30037150, 2018). "MiR 93, shown here to be decreased in the first few months following surgery, inhibits glucose transport and is overexpressed in insulin-resistant women with polycystic ovary syndrome." (PMID 29881628, 2018). "We aim to assess the effects of metformin treatment on metabolic and endocrine parameters and genes expression related to the insulin-responsive pathway in polycystic ovary syndrome (PCOS)." (PMID 29430464, 2017).
polycystic ovary syndrome (continued). "Polycystic ovary syndrome (PCOS), a complex endocrine disorder characterized by androgen excess, menstrual irregularities and ovulatory disturbances, is often associated with obesity (particularly abdominal adiposity) and insulin resistance." (PMID 28611442, 2017). "Metformin, the drug which causes sensitization to insulin (ISD), apart from diabetes treatment, has also been introduced for the therapy of polycystic ovary syndrome (PCOS)." (PMID 28589443, 2017). "This study was carried out to evaluate the effects of vitamin D supplementation on the metabolic profiles of insulin-resistant subjects with polycystic ovary syndrome (PCOS)." (PMID 29186759, 2017). "Mito-Ob mice showed morphologically distinct polycystic ovaries and elevated estradiol, but normal testosterone and insulin levels." (PMID 28432106, 2017). "Furthermore, polycystic ovary might arise due to primary defect in the ovary and overgrowth of periovarian adipose tissue, independent of factors normally implicated in its development such as increased androgens and insulin levels." (PMID 28432106, 2017). "Our findings of normal insulin levels and insulin sensitivity, along with anovulation and polycystic ovaries, in Mito-Ob mice prompted us to measure LH and testosterone levels in female Mito-Ob mice." (PMID 28432106, 2017). "It is known that the weight loss following bariatric surgery increases the fertility rate, both in men and women, for a number of reasons, and it is also an important factor of improvement in insulin sensitivity and polycystic ovary syndrome in women." (PMID 26910630, 2016). "Because insulin is one of the major regulators of lipoprotein lipase activity and hyperandrogenemia has an independent role in lipoprotein and lipid metabolism, differences in lipid levels in various studies are somewhat influenced by these factors." (PMID 27351028, 2016). "In women with polycystic ovary syndrome, circulating irisin levels correlated with the area under the curve of insulin secretion and HOMA-IR." (PMID 27472279, 2016). "It is proved that EA can normalize insulin sensitivity of polycystic ovary syndrome rats by increasing skeletal muscle cytoplasmic GLUT4 content." (PMID 27656242, 2016). "The main endocrine derangements responsible for the clinical manifestations are hyperandrogenemia and abnormal insulin response to glucose." (PMID 25114670, 2014). "The author concluded that berberine, in comparison to metformin, showed similar metabolic effects presumably on amelioration of insulin sensitivity and reduction of hyperandrogenemia." (PMID 23866924, 2013). "Postmenopausal women may benefit from discussions regarding cardiovascular protective hormone replacement therapy, while patients with polycystic ovary syndrome require a consideration of insulin-sensitizing therapies." (PMID 40943815, 2025). "Moreover, MI has an insulin-mimetic effect, which was observed in several human studies with insulin-resistant patients who suffered from polycystic ovary syndrome and were treated with oral MI supplementation." (PMID 40427270, 2025). "Probiotics have also been hypothesized to modulate insulin sensitivity and hormone status, crucial factors in the pathogenesis of acne, particularly in those with insulin resistance or polycystic ovary syndrome (PCOS)." (PMID 41416302, 2025). "Additionally, the core features of PCOS, including irregular cycles, polycystic ovary morphology, increased adiposity, insulin resistance, hormonal imbalances, and chronic inflammation, further complicate the production and effects of these molecules." (PMID 40911578, 2025). "Addressing the linkages between the three, metformin can treat hyperandrogenemia by lowering insulin levels, whereas rosiglitazone may work by directly improving androgen sensitivity to insulin." (PMID 40410881, 2025).
polycystic ovary syndrome (continued). "Moreover, curcumin can effectively reduce the complications related to oxidative stress in patients with polycystic ovary syndrome and improve insulin sensitivity." (PMID 40842497, 2025). "In women with polycystic ovary syndrome, lower GI and GL diets have been shown to improve insulin sensitivity, lipid metabolism, and androgen profiles, representing a valuable non-pharmacological strategy for mitigating both reproductive and metabolic complications." (PMID 41305646, 2025). "Similarly, both androgenic progestins (frequently utilized in hormonal contraceptives) and states of hyperandrogenism, as clinically seen in polycystic ovary syndrome (PCOS), have been associated with impaired insulin sensitivity." (PMID 40676752, 2025). "Thus, it cannot be excluded that hyperandrogenemia and impaired insulin sensitivity in CAH reciprocally potentiate their cardiometabolic effects, forming a mechanism of a vicious circle." (PMID 39240753, 2025). "Abnormal insulin signal transduction pathways, especially glucose transport defects, could impair glucose disposal, induce a hyperglycemic state, and enhance hyperandrogenemia and inflammatory response." (PMID 38200540, 2024). "Subsequently, the research focus shifted to “insulin sensitivity”, with an increasing emphasis on cellular and molecular levels, covering areas such as “oxidative stress”, “skeletal muscle”, and “polycystic ovary syndrome”, as well as the adoption of “pathophysiological” research methods." (PMID 39092232, 2024). "Additionally, they improve insulin sensitivity and lipid profile, which is particularly beneficial for women with polycystic ovary syndrome." (PMID 39683470, 2024). "Consequently, pharmacological agents that enhance insulin sensitivity have been incorporated into therapeutic regimens for polycystic ovary syndrome." (PMID 38276279, 2024). "Furthermore, the favorable metabolic effects of low-carbohydrate diets have been documented in conditions such as polycystic ovary syndrome, where improvements in insulin resistance, body weight, and lipid profiles have been observed." (PMID 39834467, 2024). "Insulin inhibits the aromatase enzyme in human trophoblasts, which may result in a placental contribution to maternal hyperandrogenemia." (PMID 38541997, 2024). "We did not investigate menstrual status, but insulin resistance is associated with hyperandrogenemia rather than menstrual irregularity." (PMID 38491191, 2024). "The studies on the association between carbohydrates and infertility indicate that both quantity and quality of dietary carbohydrates affect glucose metabolism and insulin sensitivity in healthy individuals as well as in diabetics and women with polycystic ovary syndrome (PCOS)." (PMID 37823091, 2023). "Additionally, rodent models of PCOS can model many characteristics of the human disorder including hyperandrogenism, elevated LH, disrupted cyclicity, presence of follicular cysts/polycystic ovaries, and altered insulin sensitivity." (PMID 36653487, 2023). "Polycystic ovarian syndrome (PCOS), the most prevalent cause of anovulation that affects about 70% of anovulatory women, may be improved by significant weight loss to lowering insulin sensitivity." (PMID 37937052, 2023). "However, the two most proposed core etiologies are the disruption of insulin metabolism and hyperandrogenemia, both of which begin to intertwine and propagate each other in the later stages of the disease." (PMID 36834549, 2023). "A randomized, double-blind, placebo-controlled trial was conducted to evaluate the effects of saffron on inflammation markers, lipid levels, insulin, and cardiac protection in women diagnosed with polycystic ovary syndrome (PCOS) (Rahimi, Shams & Aslani, 2022)." (PMID 37404473, 2023).
polycystic ovary syndrome (continued). "Increased insulin sensitivity and glucoregulation, in turn, may lower androgen synthesis and hyperandrogenemia in women with PCOS, potentially halting the disease process (premature follicle growth arrest) and menstrual irregularity." (PMID 35547420, 2022). "The therapeutic potential of this medicament, which is most likely induced by the improvement in insulin sensitivity, is employed in different conditions, including cardiovascular diseases, diabetic nephropathy, polycystic ovary syndrome (PCOS), and the prevention or treatment of cancer." (PMID 35158846, 2022). "Therefore, metformin is often used to improve insulin sensitivity in patients with polycystic ovary syndrome." (PMID 35992123, 2022). "Recent clinical studies have found that complementary herbal treatments with cinnamon regulate the frequency of menstrual cycles and may reduce insulin resistance in women with polycystic ovaries." (PMID 34045956, 2021). "This corroborates previous studies, suggesting that amino acid metabolism plays a role in other insulin resistant states (e.g., polycystic ovary syndrome) and may influence insulin signalling and β-cell function." (PMID 34073737, 2021). "Thefindings of various studies have shown that administration of myo-inositol in patients with polycystic ovary syndrome (PCOS) undergoing assisted reproductive techniqueshas positive effects on insulin sensitivity, oocyte maturation, egg quality, and pregnancy rate." (PMID 33892722, 2021). "Polycystic ovary syndrome may provide useful clinical insights into the relationship between androgen excess, insulin signalling and metabolic dysfunction." (PMID 33816477, 2021). "Therefore, metformin is used to regulate insulin secretion and achieve the purpose of effectively improving polycystic ovary syndrome." (PMID 33014044, 2020). "In order to explore the effect of prenatal androgen exposure and of adult hyperandrogenemia on insulin we studied insulin secretion and sensitivity before and after a single dose of testosterone in ovariectomized ewes, exposed and not exposed prenatally to testosterone." (PMID 31941959, 2020). "For example, in previous work with women with endocrine abnormalities (i.e., polycystic ovary syndrome), a longer (16 weeks) low-glycemic index pulse-based diet (using identical meals as the current study) reduced insulin concentrations during an oral glucose tolerance test." (PMID 32384719, 2020). "Previous studies suggested that inositol may significantly decrease insulin levels in women with polycystic ovary syndrome (PCOS) when administered as one of the two isomer forms, myo-inositol or D-chiro-inositol." (PMID 32646482, 2020). "In the present study, a brief hyperandrogenemia reduced the ISI-C only in ewes that were prenatally exposed to testosterone, suggesting that hyperandrogenemia may decrease peripheral sensitivity to insulin." (PMID 31941959, 2020). "The production of polycystic ovary syndrome is directly related to the abnormality of insulin." (PMID 33014044, 2020). "Exercise can reduce androgen and insulin levels in polycystic ovary syndrome (PCOS) patients." (PMID 31001337, 2019). "In addition, it is helpful to improve hyperandrogenemia and insulin sensitivity via inhibiting hepatic glucose production, increasing peripheral glucose uptake and utilization, and decreasing insulin levels." (PMID 31367235, 2019). "Taken together, these results suggest that insulin contributes to PCOS hyperandrogenemia even when insulin levels are normal and that women may develop PCOS because of androgenic hyperresponsiveness not only to ACTH and LH but also to insulin." (PMID 29971102, 2018). "We and others have observed that young girls predisposed to polycystic ovary syndrome (PCOS) display defective insulin sensitivity, beta-cell function and non-esterified fatty acids (NEFA) suppressibility during early pubertal years, compared to controls." (PMID 28738839, 2017).